FAP (fibroblast activation protein alpha)
Diseases named in the same sentence as FAP in open-access papers (continued):
Sharing a sentence is not in itself a finding about the gene and the disease.
tumor (continued). "Further analysis revealed a trend between connective tissue and tumor area, where FAP has a reverse relation with FN1 on tissue location, which is in accordance to the negative correlation between FAP and FN1 in TCGA seq data on FAPhigh TC cells." (PMID 41233863, 2025). "FAP, a key marker of CAFs, has been identified as a potential therapeutic target due to its role in tumor-stroma interactions." (PMID 40486595, 2025). "This study underscores the pivotal role of FAP in driving TC progression, specifically by enhancing tumor cell migration, invasion and immune cell infiltration, while regulating PD-L1, HLA-I and my-CAF subpopulations." (PMID 41233863, 2025). "In contrast, in FL, all but one patient (91%) presented with lower tumor tissue FAP and higher serum sFAP levels." (PMID 41373408, 2025). "Taken together, these data suggest activin co-localization in the TME promotes CD163 and FAPα expression to facilitate a tumor- tolerant environment." (PMID 40075112, 2025). "Consistent with this idea, several studies in murine cancer models demonstrate that targeting FAP and consequent depletion of CAFs, enhances anti-tumor activity and lymphocyte infiltration." (PMID 41345672, 2025). "For instance, in PDAC, the desmoplastic stroma makes up 60-70% of the tumor volume and prominently features FAP-expressing CAFs that influence fibrosis, tumor spread, and treatment resistance." (PMID 39572227, 2025). "Integrated single-cell and spatial transcriptomics in rectal cancer, CAF polarization dictates chemotherapy response, with tumor-suppressive CAFs organizing protective immune networks and FAP+ CAFs driving EMT." (PMID 40693266, 2025). "Our data indicated that FAP/IL-15 CAR-T cell treatment significantly suppressed tumor growth and prolonged survival in xenograft-bearing mice compared to FAP CAR-T cells, FAP CAR-T cells combined with exogenous IL-15, and other controls." (PMID 41455698, 2025). "The target structure is the fibroblast activation protein (FAP), a membrane-bound peptidase, which is increasingly expressed in cancer activated fibroblasts (CAFs) in the stroma of tumor cells." (PMID 40272498, 2025). "Our findings provide robust preclinical evidence supporting the targeted elimination of both CAFs and tumor cells positive for FAP by FAP/IL-15 CAR-T cells, underscoring their potential utility as adoptive cellular immunotherapies." (PMID 41455698, 2025). "Recent findings suggest that FAP’s effects on tumor behavior extend beyond its catalytic activity through protein interactions, adding complexity to its role in cancer biology." (PMID 41373408, 2025). "By combining Nivolumab with CAF-targeting agents, such as TGF-β inhibitors or FAP inhibitors, the therapy can simultaneously reduce the immunosuppressive effects of CAFs and enhance the immune response against tumor cells." (PMID 40909292, 2025). "Fibroblast activation protein (FAP), a transmembrane serine protease expressed primarily in pathological conditions, plays a pivotal role in tumor progression." (PMID 41373408, 2025). "Preclinical studies have demonstrated that targeting FAPα can lead to substantial reductions in tumor volume, the suppression of metastatic potential, and enhanced survival outcomes." (PMID 40918451, 2025). "Other novel approaches include monoclonal antibodies conjugated with cytotoxic agents or bispecific antibodies that target both FAP on CAFs and death receptor 5 on tumor cells, showing potent antitumor effects." (PMID 40313969, 2025). "FAPI pseudopeptides, such as FAP-2286 and 3BP-3940, are emerging as leading theranostic agents for targeting the tumor microenvironment." (PMID 40766056, 2025). "FAP immunohistochemistry (IHC) was performed on primary tumor specimens and correlated with key clinicopathological features, disease-free survival (DFS), overall survival (OS), and radiological response to first-line tyrosine kinase inhibitors (TKIs)." (PMID 41303595, 2025).
tumor (continued). "Among these, [68Ga]Ga-FAPI-46 has demonstrated excellent performance in oncologic imaging, with high tumor-to-background contrast and strong correlation between tracer uptake and FAP expression." (PMID 41155591, 2025). "Fibroblast activation protein (FAP), a dipeptidyl peptidase 4 protein, has limited expression in normal adult tissues, but is overexpressed on CAFs in a variety of tumor stroma of many epithelial tumors and can specifically target tumor stroma." (PMID 40457405, 2025). "Biomolecules, such as FAP, which contribute to tumor progression and offer a promising target for cancer therapy, were rarely considered when building 3D tumor models." (PMID 40704837, 2025). "Based on the significance of FN1 in the ECM formation, its association with stroma and the enzymatic activity of FAP on FN1, the TMA was stained for FAP and FN1 and their expression was evaluated in tumor (Tm) and connective tissues (CT)." (PMID 41233863, 2025). "This study primarily aims to investigate the extent to which sFAP competes with tumor-bound FAP and its impact on the pharmacokinetics of FAPI-radiopharmaceuticals." (PMID 40000459, 2025). "In contrast, the presence of FAP in the tumor stroma was frequently observed throughout the cohort, particularly in high-grade serous EOC with 42% of stFAP-high cases." (PMID 41466165, 2025). "Time-dependent accumulation of [89Zr]Zr-H4-Fc, [89Zr]Zr-H15-Fc and [89Zr]Zr-H17-Fc at FAP-expressing tumor sites was evident over the course of the 96-h study, while tumor localization of [89Zr]Zr-NGS2405-Fc rapidly plateaued within 24 h." (PMID 40804296, 2025). "Another possible mechanism is that FAP selectively cleaves type I collagen, leading to increased macrophage adhesion, which in turn promotes tumor progression." (PMID 40520892, 2025). "FAP, which is overexpressed in CAFs, is one of the most classical markers to study the relationship between CAFs and tumor progression." (PMID 40457405, 2025). "Subsequent studies have consolidated these results, extending the potential applications of [68Ga]Ga-FAP-2286 to other tumor types such as urothelial and lung cancers." (PMID 40766056, 2025). "Comparison between two radiolabeled Nb constructs, [89Zr]Zr-Nb159 (~ 15 kDa) versus [89Zr]Zr-PEG-Nb159 (~ 36 kDa), revealed distinct pharmacokinetic profiles in FAP+ tumor-bearing mice." (PMID 41460404, 2025). "FAP was significantly overexpressed in tumor tissues compared to normal tissues (P < 0.001), with expression levels increasing alongside clinical stage and T-stage (P < 0.05)." (PMID 41244835, 2025). "Targeting components of the tumor microenvironment, such as fibroblast activation protein (FAP) on stromal cells, can indirectly affect tumor growth and survival and overcome tumor heterogeneity." (PMID 40861448, 2025). "These BsAbs target both tumor antigens and stromal or vascular components such as fibroblast activation protein (FAP) or vascular endothelial growth factor (VEGF), aiming to remodel the TME." (PMID 41476945, 2025). "We further investigated the correlation between tumor stiffness and the expression levels of HE4 and fibroblast activation markers (α-smooth muscle actin (α-SMA) and fibroblast activation protein (FAP)) in tumor tissues from 22 HGSOC patients." (PMID 41502510, 2025). "Essentially, FAP is a marker for activated stromal CAFs, facilitating tumor microenvironment remodeling, whereas Ki67 is a proliferation marker of tumor cells, reflecting cell division activity." (PMID 41408360, 2025). "At the same time, FAP is recognized as a common CAF marker that is frequently employed to discern activated fibroblasts actively shaping the tumor microenvironment." (PMID 39950116, 2025). "High FSTL1 level in FAP positive fibroblasts is associated with poor patient prognosis, and targeting FSTL1 can inhibit tumor malignancy and extend survival in tumor-bearing mice." (PMID 40755769, 2025).
tumor (continued). "CAR T‐cell therapies for PM have primarily targeted several specific tumor‐associated antigens, including MSLN, placental alkaline phosphatase‐like 2 (ALPPL2), fibroblast activation protein (FAP), and MET." (PMID 40904706, 2025). "Targeting components of the tumor stroma (e.g., FAP, PDGFRβ), which exhibit lower antigenic variability, is also under investigation." (PMID 41262250, 2025). "Fibroblast activation protein (FAP) is overexpressed in the tumor micro-environment in up to 90% of epithelial tumors and has limited expression in healthy tissues." (PMID 41463267, 2025). "These pharmacokinetic properties, coupled with the limited expression profile of FAP, yielded significant tumor-to-serum and tumor-to-liver ratios of 9:1 and 21:1, respectively." (PMID 40542914, 2025). "In DLBCL, most patients (78%) presented with higher tumor tissue FAP expression and lower serum sFAP levels." (PMID 41373408, 2025). "Time-dependent accumulation of [89Zr]Zr-H4-Fc, [89Zr]Zr-H15-Fc and [89Zr]Zr-H17-Fc at FAP-expressing tumor sites was evident over the course of the 96-hour study, while tumor localization of [89Zr]Zr-NGS2405-Fc rapidly plateaued within 24-hours." (PMID 39868181, 2025). "FAP, a serine protease overexpressed on CAFs in multiple tumor types, has become a leading candidate." (PMID 40534854, 2025). "Chimeric antigen receptor (CAR)-T cells specific for murine FAP were shown to deplete FAP-expressing stromal cells, reducing tumor growth in mice." (PMID 40893164, 2025). "FAP expression on tumor cells was found in 10% of all EOCs, while stromal FAP was seen in 47% of the cases, with the highest prevalence in high-grade serous EOC (42%)." (PMID 41466165, 2025). "FAP, as a pan-tumor target, is consistently expressed in mesenchymal cells, potentially addressing tumor heterogeneity caused by genetic mutations in cancer cells." (PMID 40438601, 2025). "Background/Objectives: Fibroblast activation protein (FAP) is highly expressed in tumor stroma and selected inflammatory conditions, offering a promising target for molecular imaging." (PMID 41155591, 2025). "An observational study of 64 patients concluded that SUVmax increases with tumour FAP expression and was a more accurate tool when compared to CT and [18F]FDG PET/CT." (PMID 40069442, 2025). "Fibroblast Activation Protein (FAP)-targeted RLT agents bind FAP, a transmembrane serine protease selectively expressed on cancer-associated fibroblasts, which are present in the tumour microenvironment of approximately 90% of solid tumours." (PMID 41228206, 2025). "The in vivo anti-cancer immune response of FAP-IL2v in various combination immunotherapies was investigated in both xenograft and syngeneic murine tumor models." (PMID 39852848, 2025). "A separate case series of nine patients with high FAP expressing advanced solid tumors treated with 90Y-FAPI-46 reported favorable tumor uptake and disease control in ~50% of patients, although grade 3–4 hematologic toxicity occurred in four cases." (PMID 41441395, 2025). "Recent developments in targeted delivery of radionuclide to tumours by anti-FAP peptides or inhibitors have shown great promise." (PMID 39780187, 2025). "In our study, we explored the relationship between FAP+ fibroblasts and multiple tumor infiltrating immune cell types in PCa." (PMID 40438108, 2025). "On the other hand, the targeted elimination of FAP+α‐SMA+ CAFs leads to enhanced tumor stemness and increased infiltration of Treg cells, accelerating tumor progression." (PMID 40656546, 2025). "Recently, FAP inhibitors have been developed as diagnostic tracers, and FAPI PET imaging has shown tumor-specific diagnostic performance in many cancers." (PMID 40126602, 2025). "Consistent with our experimental data we confirmed that indeed higher FAP expression was observed in tumour tissue compared with normal kidney tissue." (PMID 41303595, 2025).
tumor (continued). "For example, FAP-2286, a novel radioligand therapy, demonstrated favorable tumor uptake in a phase I study (NCT04939610) for advanced solid tumors." (PMID 40909292, 2025). "The experimental animal model used in this study exhibited dynamic changes in PSMA and FAP expression as the tumor progressed, underscoring the importance of timely tissue sampling for IHC analysis in clinical practice." (PMID 40430845, 2025). "A lower FAPI-PTV signifies a reduced tumor burden with a small FAP-active lesion among the total lesions, indicating a greater likelihood of achieving pCR after NAT." (PMID 41268551, 2025). "The role of FAP extends beyond molecular interactions influencing broader tumor behaviors and microenvironmental interactions by its enzymatic cleavage of FN1, which affects the availability and activation of TGF-β." (PMID 41233863, 2025). "These trials demonstrate that [177Lu]Lu-FAP-2286 has a favorable safety profile, with manageable side effects and long tumor retention." (PMID 41463267, 2025). "Fibroblast Activation Protein (FAP) has emerged as a critical player in cancer biology, particularly in shaping the tumour microenvironment (TME) and influencing immunotherapy outcomes." (PMID 40741380, 2025). "Al18F-NOTA-FAP-2286 PET/CT imaging in U87 tumor-bearing mice revealed accurate targeting of high FAP-expressing xenografts." (PMID 40430845, 2025). "Fluorescence imaging, often utilized in intraoperative settings, benefits from FAP's strong stromal localization, allowing surgeons to more precisely delineate tumor margins." (PMID 40656546, 2025). "Although FAP-2286 showed promising anti-tumor activity in tumor models, significant renal uptake was observed in patient imaging evaluations of 68Ga-FAP-2286." (PMID 40438601, 2025). "Experiments in the HT1080 FAP model showed that the 86Y-FAPI-C16 was still well accumulated in the tumor at 48 h." (PMID 40438601, 2025). "Albumin-binding FAP radioligands like 68Ga-FSDD3I further enhance tumor uptake and retention time, offering high-quality imaging in PET scans." (PMID 39911388, 2025). "We found that in tumor tissues, FAP+ and MFAP5+ fibroblasts have most communication pathways with TAMs, suggesting that FAP+ and MFAP5+ fibroblasts play an important regulatory role within the TME." (PMID 40438108, 2025). "177Lu-FAP-2286 demonstrates superior tumour retention due to the extended half-life (6.65 days) of lutetium-177, enabling prolonged radiation exposure to FAP-positive malignancies." (PMID 40725089, 2025). "Agents like αFAP-PE38 and radiolabeled antibodies (e.g., 177Lu-ESC11, 177Lu-ESC14) have shown the ability to deplete FAP+ stroma and suppress tumor growth in preclinical models." (PMID 41441395, 2025). "CAR-T cell therapy has the characteristics of self-expansion and higher sensitivity to low antigen expression, thus having the potential to become a promising alternative strategy for targeting fibroblast activation protein (FAP) tumor stromal cells." (PMID 40038745, 2025). "The successfully prepared PC3‐PSCA/HT1080 hFAP 3D multi‐spheroid tumor models comprise tumor cells, an artificial supporting matrix, and FAP‐providing cells, which can be cultured for ≈20 days." (PMID 40704837, 2025). "[68Ga]Ga-FAPI-46 is a DOTA-based FAP inhibitor with excellent tumor-to-background ratio and potential advantages over [18F]FDG in low-glycolytic tumors." (PMID 41155591, 2025). "This subpopulation has been observed to enhance EMT and ECM remodeling, with high glycolytic activity and interactions with tumor cells and FAP+ fibroblasts contributing to metastasis and therapy resistance, particularly in liver and lymph nodes." (PMID 40918451, 2025). "Preclinical and early-phase clinical studies in other tumor types have evaluated FAP-directed approaches—including monoclonal antibodies, CAR-T cells, and enzymatic inhibitors—with encouraging outcomes." (PMID 41303595, 2025).
tumor (continued). "This process drives increased lactate production by FAP+ CAFs, which is then transported into the tumor microenvironment via MCT4." (PMID 40855046, 2025). "The genetic deletion, vaccination, and pharmacologic inhibition of FAP suppress tumor growth and reshape the tumor microenvironment in preclinical models." (PMID 40643502, 2025). "FAP + CAFs and tumor-infiltrating lymphocytes (TILs) were significantly concentrated at the tumor periphery." (PMID 39751643, 2025). "We then performed a correlation analysis between ACTA2 and FAP with the cfRNA‐defined subtype markers in tumor gene expression data from the COMPASS trial." (PMID 39478658, 2025). "Recently, several therapeutic approaches have been developed to target FAP+ CAFs, aiming to overcome tumor immunosuppression." (PMID 41154405, 2025). "Our results showed that tumor progression in the FAP- CAFs + lactate group was significantly accelerated compared to the FAP- CAFs + DMSO group, with lower infiltration and cytotoxic capacity of CD8-positive T cells." (PMID 40855046, 2025). "177Luwas delivered to the tumor via FAP-targeting antibodies, followedby the injection of the prodrug OxaliPt­(IV)-Gem." (PMID 40893960, 2025). "The advent of FAP inhibitor (FAPI)-based positron emission tomography (PET) imaging has established FAP as a promising pan-tumor target for radioligand therapy (RLT)." (PMID 41425958, 2025). "Compared with their wild-type counterparts, both CEA-IL2v and FAP-IL2v demonstrated improved tumor-to-organ ratios and enhanced pharmacokinetic profiles in preclinical studies." (PMID 41568361, 2025). "FAP is expressed by CAFs which contribute to immune suppression in the TME directly by promoting regulatory T cells (Tregs) and tumour-associated macrophages via secreted cytokines and indirectly by ECM remodelling and creating a physical barrier." (PMID 40741380, 2025). "To date, tumor-directed delivery of IL-15/4-1BBL (scFv anti-FAP), IL-2/TNF (scFv anti-EDA) and IL-2/IL-12 (scFv-Fc anti-CD30, LAIR2), has shown significant therapeutic effects in preclinical tumor mouse models." (PMID 40370435, 2025). "showing the enhanced tumor‐specific T‐cell infiltration and 4 T1 tumor regression following the targeted destruction of FAP‐alpha‐expressing CAFs using ferritin NPs conjugated to FAP‐alpha‐scFv." (PMID 40970572, 2025). "Despite the low tumor mean absorbed dose due to the poor FAP expression, pretargeting delayed tumor growth and extended survival in the pretargeted cohort (3 × 88 MBq) compared to controls." (PMID 40131608, 2025). "For example, fibroblast activation protein (FAP)-targeting vaccines have demonstrated potential in breast cancer by eliciting immune responses that eliminate CAFs and attenuate tumor growth." (PMID 40784879, 2025). "Tumor cell expression of FAP (tFAP) was evaluated in n = 158 cases, where 10% (n = 16) of tumors displayed membranous tFAP expression." (PMID 41466165, 2025). "FAP inhibitor (FAPI) radiopharmaceuticals are considered to be the most promising to be developed for targeting FAP due to their rapid and specific tumor targeting." (PMID 40438601, 2025). "In recent years, there has been growing interest in targeting the tumor microenvironment, particularly through fibroblast activation protein (FAP) inhibitors (FAPIs)." (PMID 40766056, 2025). "We found patients with higher CAF-FAP (FAP+VIM+) at tumor core or lower CAF-C7 (PDGFRA+VIM+) at tumor margin exhibited worse survival (tumor core, n = 154, P = 0.036; tumor margin, n = 148, P = 0.037)." (PMID 39870619, 2025). "DNA vaccines against FAP reduced tumor growth and stromal collagen in animal models, improving drug delivery and reducing fibrosis without systemic inflammation." (PMID 41441395, 2025). "During liver carcinogenesis, FAP promotes fibrosis in response to early liver injury, then facilitates tumor cell proliferation, and contributes to immune suppression 117-119." (PMID 40303292, 2025).